CDK6 (cyclin dependent kinase 6)
Diseases named in the same sentence as CDK6 in open-access papers (continued):
Sharing a sentence is not in itself a finding about the gene and the disease.
cancer (continued). "Among the predicted targets of miR-29b such as signal transducer and activator of transcription 3 (Stat3), cyclin-dependent kinase 6 (CDK6), lysine demethylase 2A (KDM2A) and Sirtuin-1 (SIRT-1), SIRT-1 was reported to be associated with chemoresistance in cancers." (PMID 29552311, 2018). "Of note, the concomitant downregulation of D3 and CDK6, recently reported, might disrupt the cancer-specific metabolic pathways (pentose and serine), and therefore deprive the cells of pivotal molecules such as NADPH and glutathione." (PMID 29137335, 2017). "Our data, showing that CDK6 phosphorylates and thereby stabilizes FOXO3, are highly reminiscent of the effects elicited on FOXM1, a related transcription factor, that, following phosphorylation by CDK4 and CDK6, is stabilized and transactivated to prevent senescence of cancer cells." (PMID 28778953, 2017). "Because CDK4 plays an important role in G1/S phase transition by associating with CDK6, deregulation of the CDK4/6 signaling pathway is one of the most common changes found in human cancers, including NSCLC, CDK4/6 were also considered the most desirable targets for cancer therapies." (PMID 27049724, 2016). "CDK6 activation can directly lead to some of the hallmarks of cancer by causing proliferation that is independent of normal extracellular cues or by over-riding checkpoints that ensure genomic integrity and stability." (PMID 27230400, 2016). "Loss of MIR-491 could regulate IGFBP2, CDK6 and EGFR proliferative pathways, by which the propagation of GBM cancer stem cells was inhibited." (PMID 27905892, 2016). "Additionally, Hu et al18 found that CPEB4 was strongly induced by the important erythroid-related transcription factors Gata1 and Tal1 and that 1 CPEB4 target gene is CDK6, an important protein in cell cycle regulation and cancer development." (PMID 26166131, 2015). "In contrast, cancers that lack Rb function may be resistant to CDK4/CDK6 inhibition because the antitumor effect of CDK4/CDK6 inhibition is partly due to downstream Rb phosphorylation." (PMID 25914884, 2015). "A comparison of this list with known human cancer driver genes revealed Cdk6 and Ikzf1 (Ikaros) as two genes whose amplifications may drive tumorigenesis." (PMID 25452272, 2014). "Thus, our current study revealed what we believed to be a novel upstream regulatory mechanism of CDK6 in cancer cells." (PMID 25178497, 2014). "As expected, overexpression of cdk4, cdk6, or their regulatory D-type cyclins in cultured cells often leads to accelerated cell growth and their dysregulated function has been observed in many forms of cancer." (PMID 24848372, 2014). "In addition, miRNA-29-a is well known of oncosuppressor miRNA, which is frequently lost or down-regulated in cancer so that target oncoproteins like CDK6, MCL1, or BCL-2 can be upregulated." (PMID 24521303, 2013). "Upregulation of cyclin D2 and CDK6 has been observed in cancers." (PMID 23024765, 2012). "Important cancer related genes identified for this phenotype are CDK6 gene, which inhibits proliferation of human mammary epithelial cells; SIAT4C, which is down-regulated in RCC, RHOB, which is known to be a pro-apoptotic and tumor suppressor gene, and the FLT1 and TFF3 gene." (PMID 19458770, 2007). "Consequently, CDK6 represents a promising target for anti-cancer therapy." (PMID 37298284, 2023). "However, our studies showed that only inactivation of STING but not MAVS, could reverse the higher levels of ISG expression in Cdk4−/− and Cdk6−/− cancer cells." (PMID 37833461, 2023). "Cdk6−/− MCA205 cells proliferated at a slower rate and formed fewer colonies than WT and Cdk4−/− MCA205 cells, indicating Cdk6-deficiency could directly affect cancer cell proliferation in vitro." (PMID 37833461, 2023).
cancer (continued). "It should also be considered that CDK6 is also present in the “regulation of cell differentiation” pathway, as long as Bcl2 is included not only in “negative regulation of apoptotic processing” but also in “regulation of cell differentiation” and “pathway in cancer”." (PMID 36498866, 2022). "Due to the decreased ABCB1 transporter expression, cdk6-deficient KB-C2 cells achieved remarkable reversal of MDR, showing significant increase in sensitivity to ABCB1 substrates colchicine and paclitaxel, demonstrating that CDK6 regulates cancer MDR mediated by ABCB1 specifically." (PMID 35459184, 2022). "Native CDK6 may have a role in maintaining ABCB1-mediated MDR of cancers." (PMID 35459184, 2022). "Meanwhile, knockout of cdk6 could inhibit cancer cell proliferation and malignancy." (PMID 35459184, 2022). "Additionally, the expression of p16, which is known as intracellular CDK4 and CDK6 inhibitor, was downregulated in five out of eight cancer cell lines after combination treatment, but might be triggered mainly by IR." (PMID 34722291, 2021). "Further development is expected to yield second-generation PROTACs combining superior ex vivo activities (inhibition of CDK6-regulated S phase; CDK6 degradation) with improved pharmacokinetic properties that might establish these drugs as bona fide anti-cancer therapeutics." (PMID 34573335, 2021). "Furthermore, significantly elevated expressions of CDK2, CDK4, and CDK6 are well documented in HCC and many other cancers, and they are the causal factors for the development and progression of cancer." (PMID 33579185, 2021). "Thus, cdk4, cdk6, e2f1, and rb1 not only participate in the progression of cancer cells but might also be useful biomarkers for predicting prognosis in some tumors." (PMID 32357912, 2020). "Thus, targeting CDK6 by EA can be a smart therapeutic approach to manage CDK6 directed cancers." (PMID 32429317, 2020). "Thus, the identification of a selective CDK-6 inhibitor may be used as therapeutic targeting of cancer cell growth and metabolic alterations." (PMID 32429317, 2020). "Additionally, CDK4 and CDK6 are known to be expressed by both cancer models." (PMID 31548560, 2019). "Therefore, downregulation or inhibition of Chk1, Chk2, cyclin D1, and CDK6 could be an innovative target for cancer treatment." (PMID 32010609, 2019). "Therefore, CDK6 is considered as a promising target for anti-cancer treatment." (PMID 29715320, 2018). "circRNA_100290 worked as a miRNA sponge for several members of the miR-29 family, decreasing the quantity of available miR-29s and, accordingly, promoting translation of one of their targets, CDK6 (cyclin-dependent kinase 6), which in turn could induce transition from G1 to S phase in cancer." (PMID 29147648, 2017). "In addition to the inflammation pathway, several cancer-related pathways were identified from the global NSAIDs-regulating miRNA-gene subnetwork, including cell cycle (CDK6, CCND1, CCKN1A, and E2F1), proliferation (MYC), apoptosis (BCL2) and angiogenesis (VEGFA)." (PMID 27329603, 2016). "Thus, CDK6 plays a critical role in RB phosphorylation and cancer growth." (PMID 24765199, 2014). "Therefore, CDK6 has been regarded as a possible target for cancer therapy." (PMID 25178497, 2014).
cancer (continued). "Given that reduced expression of p27 has been observed in several human cancers, and p27 is associated with the induction of apoptosis in cancer cells, our findings suggest that PPY may modulate the sub-G1 arrest via upregulation of p21 and p27 and downregulation of Cdk6 and cyclin E." (PMID 24970277, 2014). "Furthermore, we used loss of function approach to evaluate whether the physiological function of CDK6 was involved in miR-320c regulated cancer inhibition effect." (PMID 25178497, 2014). "Therefore, GAS5/CDK6 pathway may play an important role in regulating cancer development and progression." (PMID 24069260, 2013). "Our experiments also indicated that CDK6 and MAP3K6 are involved in regulating cancer cell proliferation, invasion, migration, wound healing, and cell cycle progression." (PMID 40278596, 2025). "Studies have found that CDK4 and CDK6 are frequently overexpressed in pediatric B-ALL patients, with cancer cells relying on this pathway for excessive proliferation." (PMID 41155287, 2025). "The widespread relevance of the FRA1 transcriptional network is evident across multiple aggressive cancer types, where FRA1 expression correlates with AXL, CDK6, and FSCN1 levels and poor patient outcomes." (PMID 41286309, 2025). "Given the fact that CDK4/6 kinase inhibitors are already used in clinics but show a number of limitations when treating certain types of cancers and the appearance of resistance mechanisms to CDK4/6 kinase inhibitors, new strategies to target CDK6 are needed." (PMID 39898030, 2025). "The key question is how the overexpressed CDK6 in cancer cells enables cell cycle progression in lieu of CDK4, and what molecular mechanisms differentiate the higher activity of CDK6 from that of CDK4." (PMID 40093074, 2025). "This investigation demonstrated that kaempferol affects cancer cells by downregulating CDK1, CDK4, CDK6, and CDK7 at both the gene and protein levels in MDA-MB-231 cells, and specifically CDK6 and CDK7 in MDA-MB-468 cells." (PMID 41463161, 2025). "Taken together, the western blot and RNA-seq data show downregulation of CDK6 in HJP 272 treated A549 cells, indicating a potential mechanism whereby this compound inhibits cancer cell progression and apoptosis." (PMID 40769056, 2025). "Cyclin-dependent kinase 6 (CDK6) was proved to be an important regulator in the progression of cell cycle and has been a promising therapeutic target in cancer treatment." (PMID 38212482, 2024). "Cyclin-dependent kinase-4 and cyclin-dependent kinase-6 (CDK4 and CDK6) are often overexpressed in cancer, including CRPC, and are considered as targets for cancer treatment." (PMID 39090086, 2024). "The possible molecular mechanism involves inhibiting cleaved CASP3, MMP3, SRC, MAPK10 and CDK6, and activating PPARα and JAK, which are typically involved in cancer pathways, the PI3K-Akt signaling pathway and viral carcinogenesis pathways." (PMID 38675723, 2024). "EIF4A inhibition in cancer cells leads to G1-arrest through translation inhibition of CDK4, CDK6 or members of the cyclin D family." (PMID 38011999, 2024). "The possible molecular mechanism involved in cancer pathways, PI3K-Akt signaling pathway and viral carcinogenesis pathway via the inhibition of CASP3, MMP3, SRC, MAPK10 and CDK6 and the activation of PPARα and JAK." (PMID 38675723, 2024). "D-type cyclins activate CDK4 and CDK6, which subsequently phosphorylate and inactivate the RB1 tumor suppressor, thereby derepressing cancer cell proliferation." (PMID 39664374, 2024). "Erik’s report illustrate the complex nature of cancer cell cycles, genes (CDK4, CDK6, CCND1, CDK2, and CCNE1) that regulate the G1/S transition yield particularly variant vulnerabilities in different cancer cell." (PMID 38582921, 2024). "This, coupled with the observed suppression of cyclin-dependent kinases (CDKs) CDK4 and CDK6 expression, hints at the crucial role of CDKs in BTZ’s anti-cancer effects." (PMID 38724504, 2024).
cancer (continued). "Cancer-related genes such as CXCR4, MMP7, CDC20 and CDK6, and unfolded protein response (UPR)-related genes such as ATF3, ATF4, XBP1 and CHOP, showed significant differences in expression in the indicated cells." (PMID 38263248, 2024). "Targeting CDK6 and the closely related CDK4 kinase has garnered significant interest for cancer therapy." (PMID 39309429, 2024). "Among these dietary phytochemicals, ellagic acid (St.36) was best located inside the binding pocket of CDK6, this compound inhibited the CDK6 with an IC50 value of 3.053 μM, as well as decreased the colonization of cancer cells and induced apoptosis." (PMID 39404419, 2024). "Highlighting the significance of interactions with extracellular growth factors such as VEGFA and IGF1 in cancer growth and progression, several targets, including CCND1, WEE1, VEGFA, and CDK6, were identified to interact with two miRNAs." (PMID 39614097, 2024). "Though increasing substrates of FBXO7 in cancer and nervous system diseases have been detected, such as Sirtuin 7 (SIRT7), cyclin-dependent kinases (CDK6) and Ubiquitously eXpressed Transcript isoform 2 (UXTV2)." (PMID 37344480, 2023). "In cancer cells, for G1 to S-phase transition in the cell cycle, CDK-4 or CDK-6 make a complex with cyclin D, and CDK-2 makes a complex with cyclin-E." (PMID 36597025, 2023). "CDK6 was upregulated in self-renewing lenvatinib-resistant HCC cells, indicating its role in the regulation of cancer stemness in HCC." (PMID 37872167, 2023). "A PPI network analysis was used to identify 17 potential targets of saponins aglycone in cancer cells, and the binding modes of saponins aglycone to four of these targets (BRD3, GLO1, CDK6, and HRAS) were confirmed using docking and MD simulations." (PMID 37996449, 2023). "Two key players of the cell cycle, CDK6 and CCND1, were connected to palbociclib, the first CDK4/6 inhibitor approved for cancer therapy." (PMID 37359725, 2023). "LRPPRC-CDK6 loop inhibition by GAA not only induced cell cycle arrest by decreasing CDK6 expression, but also suppressed OXPHOS and eliminated cancer stem cells." (PMID 37452037, 2023). "In summary, these data suggest that bis-DbTACs are effective degraders of CDK6 and CDK9, providing a basis for their potential applications in cancer treatment." (PMID 37495569, 2023). "Knockdown of CMTR1 inhibited cancer cell growth both in vitro and in vivo, with a concomitant reduction in the expression of cell cycle-related genes, such as CDKN1A, CDK6, and CCND1." (PMID 37024465, 2023). "The aberrant overexpression of CDK6 protein is the most recognized reason for CDK4/6i primary and acquired resistance for many cancers, including lung cancer." (PMID 37452037, 2023). "In this study, through promoting CDK6 mRNA stability, IGF2BP2 increased CDK6 and p-Rb levels, therefore relieving the cell cycle arrest in G0/1 phase and promoting cancer cell proliferation." (PMID 37816718, 2023). "At last, CDK6 with c-Jun upregulates VEGF-A, inducing tumor angiogenesis, thus promoting cancer progression and drug resistance." (PMID 37833875, 2023). "Analysis of RNA-seq data of Cdk4−/− and Cdk6−/− cancer cells revealed that the MCM and DNA polymerases are downregulated in Cdk4−/− cells while DNA polymerases were decreased in Cdk6−/− cells, which was validated by qPCR assay." (PMID 37833461, 2023).
cancer (continued). "In agreement with our results, all the studies showed that ZEB1‐circRNAs are upregulated in cancer; however, they identified different targets and functional axes (miR‐337‐3p/TGFBR1, mR‐195‐5p/LOXL2, miR‐448/EEF2K, miR‐200a‐3p/CDK6 and miR‐199a‐3p/PIK3CA)." (PMID 37408496, 2023). "Functionally, IGF2BP3 can bind to and maintain the stability of downstream mRNAs to promote cancer progression, such as CDK4 and CDK6." (PMID 37407973, 2023). "In the sample of patient B19, four cancer related genes CCR7, AKT1, SLIT2 and CDK6 were found with HPV integrations before treatment, and none was found after treatment." (PMID 37914994, 2023). "According to the database of COSMIC, the world's largest and most comprehensive resource for exploring the somatic mutations in human cancer, chromosome 7 included lots of well-known cancer-related genes, including EGFR, BRAF, CDK6, MET, T1F1, and so on." (PMID 35568828, 2022). "HP1γ promotes cancer cell proliferation and cell cycle progression in CRC by downregulating the expression of cyclin-dependent kinase 6 (CDK6) and p21." (PMID 35159030, 2022). "For example, we found that CDK12 is essential in ~ 30% of cancer cell lines with average effects that were similar to those of CDK4 and CDK6." (PMID 36577800, 2022). "For the other treatment targets, although some of them were previously identified in other cancers, the large majority are described here for the first time in PitNETs, such as EMT, EGFR T693 phosphorylation, CDK6 and PDL1." (PMID 36307579, 2022). "We found that CD44, CDK6, GATA4, GATA6, KLF5, and KRAS, which were amplified in TCGA STAD cohort, were amplified in cancer cell clusters." (PMID 35087207, 2022). "Cancer is characterized by uncontrolled proliferation resulting from aberrant activity of various cell cycle proteins, such as CDK4 and CDK6." (PMID 35859766, 2022). "As CDK4 and CDK6 are crucial factors in tumor cell overproliferation, CDK4/6 inhibition is a potential therapeutic mechanism in these cancers." (PMID 36033522, 2022). "Compound 18a emerged as the most potent CDK6 inhibitor (IC50 = 726.25 nM) and cytotoxic against MCF-7 (IC50 = 0.01 μM), prostate PC-3 (IC50 = 1.37 μM), lung A-549 (IC50 = 1.69 μM) cancer cell lines." (PMID 33803309, 2021). "Because of the key role of CDK6 in PFKFB4-overexpressing tumors, palbociclib administration is considered an effective strategy for this type of cancer." (PMID 34211613, 2021). "Meanwhile, the inhibition of FOXM1 repressed the expression of CDK6, CCND1, CDK2, CCNE2, E2F2, and CDC25A to arrest the cell cycle at G2 phase, which blocks the promotion of cancer-cell mitosis." (PMID 34880209, 2021). "Some cancer-related proteins were consistently changed in MNNG/HOS cells after knocking down MCM8, including the downregulation of P-Akt, CDK1, and CDK6, as well as the upregulation ofMAPK9." (PMID 33828075, 2021). "These TFs regulate critical genes (such as MAML2, CDK6, FAM84B and PTBP1) that play fundamental roles in cancer." (PMID 33537074, 2021). "In fact, it demonstrated a CDK6 IC50 value of 115.38 nM and a good cytotoxicity against breast MCF-7 (IC50 = 1.59 μM), prostate PC-3 (IC50 = 0.01 μM), lung A-549 (IC50 = 2.48 μM) cancer cells." (PMID 33803309, 2021). "Of these 348 identified HOTAIR-interacting proteins, we selected YBX1, cyclin-dependent kinase 6 (CDK6) and translationally controlled tumor protein (TCTP), which are pivotal in cancer progression for additional validation." (PMID 34266873, 2021). "CDK6 and MET showed higher alteration rates in proteomic level than the genomic level consistent across at least four cancer types." (PMID 34552204, 2021).